MMP2 (matrix metallopeptidase 2)
Diseases named in the same sentence as MMP2 in open-access papers (continued):
Sharing a sentence is not in itself a finding about the gene and the disease.
neurological diseases (17 papers, 2017 to 2025). "Here, we compared the effects of three different ITCs on ROS production and on the expression of matrix metalloproteinase (MMP)-2 and -9, which represent important pathogenetic factors of various neurological diseases." (PMID 33196947, 2021). "Also, data on the varicella zoster virus (VZV) neurologic disease in humans suggest involvement of multiple MMPs, with an increased concentration of MMP2 and to a lesser degree of MMP3 and MMP9 both in serum and CSF, as well as of MMP8 and MMP12 in CSF only." (PMID 40003967, 2025). "MMPs are known to contribute to the neuro-inflammatory response in many neurological diseases, and induction of MMP-2 is mediated by the binding of vascular cell adhesion molecule-1 on VECs to the very late activation-4 antigen expressed on T cells and macrophages." (PMID 30463256, 2018). "MMP2 and MMP9 which have numerous substrates play important roles in the nervous system during development and in the adulthood as well as after injury and have been implicated in neurological disorders and diseases." (PMID 28819302, 2017). "Similarly, intrathecal infusion of 1.0 × 106 BM-MSCs in horses did not produce changes in CSF cell count or pro-MMP2 level or cause signs of the neurological disorder." (PMID 36273220, 2022). "Additionally, while our initial focus has been on AQU-118’s effect on attenuating neuropathic pain, it would be of interest to see if other neurological disorders that implicate a caspase-3 mediated apoptotic pathway would benefit from the intervention of an orally active MMP-2/-9 inhibitor." (PMID 30769782, 2019). "We also measured MMP-2/-9 in a set of CSF samples from ALS (n = 30) and age-matched other neurological diseases (OND, n = 14)." (PMID 41009467, 2025). "MMP-9 and MMP-2 are expressed in the brain, spinal cord, and DRG, and are often increased in response to inflammation, injury, or neurological diseases." (PMID 34631222, 2021). "The current study seeks to further define MMP-2 and MMP-9 protein levels and enzyme activity in the serum and CSF of ALS and compare their levels to those in the serum of age-matched, healthy controls (HCs) and CSF of other neurological diseases (OND)." (PMID 41009467, 2025). "Furthermore, among these EMT genes, four genes (MMP2, MAP1B, SNAI2, and WNT5A) were involved in neurologic diseases." (PMID 36553576, 2022). "Interestingly, four EMT genes (MAP1B, SNAI2, MMP2, and WNT5A) were also involved in neurological diseases, brain metastasis, and response to platinum-based chemotherapy or tyrosine–kinase inhibitors." (PMID 36553576, 2022). "Interestingly, four EMT genes (MAP1B, SNAI2, MMP2, WNT5A) are also involved in neurological diseases, in brain metastasis, and interact with platinum-based chemotherapy and tyrosine–kinase inhibitors." (PMID 36553576, 2022). "In cell-conditioned medium of cortical neurons, KLK6 activated matrix metalloproteinase 2 (MMP2) and a disintegrin and metalloproteinase with thrombospondin motif 19 (ADAMTS19), all members of the proteolytic and regulatory network in neurological disorders, triggering α-synuclein processing." (PMID 34439122, 2021).
inflammation (16 papers, 2005 to 2025). Aberrant reaction of the microcirculation characterized by movement of fluid and leukocytes from the blood into extravascular tissues. "Studies have shown that raising MMP-2 levels with LPS administration causes pulmonary ECM degradation and aggravates pulmonary inflammation." (PMID 36902508, 2023). "Moreover, alirocumab not only affects lipid levels but may also offer additional cardiovascular benefits by reducing the activity of inflammatory cytokines (such as IL-18, IL-6, TNF-α) and other molecules associated with vascular inflammation (such as MMP-2, OPN, OPG)." (PMID 38017531, 2023). "Subsequently, the expression of molecules crucial for the development of vascular inflammation, including IL-6, MMP-2, MMP-9, VCAM-1, and ICAM-1, was measured." (PMID 34336088, 2021). "At day 3 post-exposure, 50 μg per mouse of Nano-Ni caused acute lung inflammation and injury that were reflected by increased neutrophil count, CXCL1/KC level, LDH activity, concentration of total protein, and MMP-2/9 protein levels and activities in the BALF." (PMID 30616599, 2019). "Taken together, IL-33 displays a central role in LPS-induced lung inflammation/injury and MMP2/9 secretion." (PMID 30410547, 2018). "In mice, airway inflammation induced by LPS is associated with an increase of the matrix metalloproteinases (MMP), MMP-2 and MMP-9." (PMID 16091136, 2005). "The aqueous extract of clove (i.p.)significantly reduced matrix metalloproteinase-2 (MMP-2) and -9 activities, neutrophil count and protein leakage into bronchoalveolar lavage fluid in an LPS-induced inflammation mouse model." (PMID 35744988, 2022).
neurodegenerative disease (16 papers, 2011 to 2025). A disorder of the central nervous system characterized by gradual and progressive loss of neural tissue and neurologic function. "MMP-2 and -9 have been widely implicated in pathogenesis of several neurodegenerative diseases including AD, HD, and ALS." (PMID 29459817, 2017). "Excessive activation of gelatinases (MMP-2/-9) is a key cause of detrimental outcomes in neurodegenerative diseases." (PMID 25859655, 2015). "Increased MMP-2 expression in cardiomyocytes, similar to the one reported in this case, has been correlated with degenerative disease in human cardiac valves." (PMID 39682376, 2024). "More than a dozen MMPs were shown to be involved in neurodegenerative diseases, including MMP-2, MMP-3, and MMP-9, and they seem to be important players in most of the diseases mentioned in this review." (PMID 26538832, 2015). "Consequently, inflammatory mediators released by activated microglia, like as IL-1β, IL-6, TNF-α, chemokines, matrix metalloproteinase 2 (MMP2), NO, and nuclear factor kappa-B (NF-κB) contribute to neurodegeneration and myelin damage in neurodegenerative diseases." (PMID 33652870, 2021). "Lastly, if active forms of MMP-2 and/or MMP-9 were present in ALS, a final goal was to determine how their levels compare to those of other inflammatory and/or neurodegenerative diseases." (PMID 41009467, 2025). "Studies have shown that cytokines released from neurons, including CCL2, CCL21, HMGB1, CGRP, Substance P, CX3CL1, MMP2, and MMP9, can mediate microglia activation in brain injury, neuropathic pain, or neurodegenerative diseases." (PMID 36131309, 2022). "Conversely, E2 treatment increased active MMP-2 and MMP-9 in SH-SY5Y neuroblastoma cells, which model neurodegenerative diseases." (PMID 33758788, 2021). "Altered levels of MMP-2 (Gelatinase A) and MMP-9 (Gelatinase B), potentially contributing to disease pathogenesis, have been shown to be altered in several neurodegenerative diseases including AD, and ALS." (PMID 29459817, 2017). "Inflammatory mediators, such as IL-1β, IL-6 TNF-α, chemokines, matrix metalloproteinase 2 (MMP2), nitric oxide, and nuclear factor kappa-B (NF-κB), contribute to neurodegeneration and myelin damage in these neurodegenerative diseases." (PMID 28555105, 2017). "MMPs, namely gelatinases MMP-2 and MMP-9, contribute to the progression of chronic and degenerative diseases." (PMID 27589705, 2016). "In contrast, genetic ablation of either MMP2 or MMP9, two major downstream targets of MT1-MMP linked to neurodegenerative diseases, did not alter memory functions in aged mice." (PMID 40983624, 2025). "Among MMPs, gelatinase-A (MMP-2) and gelatinase-B (MMP-9) are recognized as the key enzymes in the degradation of type IV collagen, the major component of basement membrane and are emerging as critically involved in chronic inflammatory and degenerative diseases." (PMID 27589705, 2016).
benign tumors (11 papers, 2011 to 2025). "Immunochemistry and Western blot analysis have shown higher activated MMP-2 in epithelial ovarian carcinomas than in benign tumors." (PMID 22200690, 2012). "The BC cases with lymph node-positive had MMP-2 expression levels that were 1.6 times higher than those with lymph node-negative BC." (PMID 37798646, 2023).
retinopathy (11 papers, 2015 to 2025). "In the EURODIAB trial, high plasma levels of MMP-2, -3, and -10 were found to be associated with severe albuminuria, however, only MMP-2 was correlated to the development and severity of retinopathy." (PMID 37092467, 2023). "Severity of retinopathy was significantly associated with higher levels of MMP-2 (p-trend = 0.017)." (PMID 25848912, 2015). "Plasma MMP-2 levels showed a significant positive association with proliferative retinopathy." (PMID 25848912, 2015). "Considering that MMP-2 has been associated with pathological NV observed in proliferative retinopathies, we decided to evaluate the DXC effect on the gelatinase activity of MMP-2 by zymography." (PMID 40230413, 2025). "Our study constitutes the first evidence of the inhibitory effect of DXC on MMP-2 enzymatic activity in both, in vitro and in vivo models, in addition to its anti-angiogenic property in proliferative retinopathies." (PMID 40230413, 2025). "Results from both mouse and rat models of oxygen-induced retinopathy suggest that MMP-2 plays a dominant role in retinal angiogenesis and that MMP-2 inhibition may be a viable therapeutic approach in ocular diseases characterized by retinal neovascularization." (PMID 37894989, 2023). "In addition, a significant trend across the severity of retinopathy was observed for increasing plasma levels of MMP-2 (p-trend = 0.017)." (PMID 25848912, 2015). "In addition, MMP-2, -3 and -10, and TIMP-1 levels were associated with macroalbuminuria, and MMP-2 was associated with proliferative retinopathy." (PMID 25848912, 2015). "Additionally, more severe retinopathy was detected in patients with higher MMP-2 concentrations." (PMID 31936869, 2020). "Previous observations have indicated the expression of matrix metallopeptidase 2 (MMP2) and IGF-1R in Muller cells during oxygen-induced retinopathy." (PMID 38300646, 2024). "Patients with microalbuminuria vs. patients with normal urine test results, and proliferative vs. nonproliferative retinopathy, had higher MMP-2 concentrations." (PMID 31936869, 2020). "In patients with retinopathy, enhanced levels of another MMP, i.e., MMP-2 were observed." (PMID 33371324, 2020). "Elevated circulating levels of MMP-2 and MMP-9 along with elevated levels of TIMP-1 were observed in patients with DR compared to diabetic patients without retinopathy." (PMID 34069322, 2021).
colorectal (8 papers, 2014 to 2023). "In summary, these data demonstrated that MMP-2 and MMP-9 correlate with worse outcomes in colorectal patients and that MnTE-2-PyP inhibits the expression of MMP-2 and MMP-9 induced by TGF-β." (PMID 30931081, 2019). "To further verify the role of MMP2 and MMP9 in pulmonary ischemia–reperfusion injury, we collected lung tissues from a mouse lung IR model for H&E staining and assessed the extent of lung injury by pathological injury scoring." (PMID 35705936, 2022).
bacterial infection (4 papers, 2021 to 2025). "Secreted MMP-2 can exert intra- and extracellular function, for example, it downregulates the activity of NF-κB inhibitor IκBα in response to oxidative stress associated with bacterial infection." (PMID 37958643, 2023). "Upon accumulation ata bacterial infection site, P1 within MPD-1 is selectively cleavedby MMP-2, causing the disassembly of the T2 CA, leadingto T1-weighted signal recovery due to removal of the quenchingpartner proximity (MRET “OFF”)." (PMID 41406353, 2025). "After exposure to MMP‐2 at the bacterial infection site, MPD‐1 disassembled into MNPs and Gd3+, and the r2/r1 ratio was decreased from 46.14 to 2.33, suggesting the switchable properties of MPD‐1 from T2 to T1‐weighted imaging owing to its response toward MMP‐2." (PMID 39036340, 2024).
metabolic disease (4 papers, 2020 to 2024). A congenital disorder (due to inherited enzyme abnormality) or acquired (due to failure of a metabolically important organ) disorder resulting from an abnormal metabolic process. "Matrix metalloproteinase-2 (MMP-2) and -3 (MMP-3), and osteopontin (OPN) are associated with adipose-tissue expansion and development of metabolic disease." (PMID 36648516, 2023).
bone disorder (3 papers, 2013 to 2023). "In humans, mutations in the gene encoding MMP-2 cause severe bone disorders in humans known as multicentric osteolysis with arthopathy, whereas MMP-2-deficient mice display only minor impairments in bone development." (PMID 23940733, 2013). "Among the factors we have identified to be dysregulated in MMP-2 deficiency many are osteoclastogenic and could potentially contribute to bone disorder in MONA." (PMID 33101055, 2020). "We found a stable profile of mRNA expression for MMP-2 and 3, TIMP-2 and -3, and a slight decline for the MMP-1 and TIMP-1 and -2 profiles during the differentiation of ASCs to osteocytes, which predispose these cells to future therapy in bone disorders." (PMID 37428795, 2023).
brain disorder (3 papers, 2022 to 2025). A disease affecting the brain or part of the brain. "Previous studies have also established a network between miR-145-5p and brain diseases, demonstrating that miR-145-5p targets MMP2 to help protect against brain injury, suggesting that miR-145-5p might be a potential biomarker of LA." (PMID 41262976, 2025).
inflammatory myopathies (3 papers, 2016 to 2023). "In human muscle, signs of peri/endomysial changes were previously found around atrophic myofibers (MMP-2 accumulation) in inflammatory myopathies." (PMID 36835504, 2023). "In this regard, upregulated MMP-9 in muscle tissue appears to be a common finding in all inflammatory myopathies, while MMP-2 seems to be affected to a lesser extent." (PMID 28042204, 2016). "This suggested that MMP-9/MMP-2 disbalance may be one of the major characteristics of myopathies." (PMID 28042204, 2016).
respiratory disease (3 papers, 2012 to 2020). "Stratification by causes of death also demonstrated that higher levels of MMP-2 were found in patients who later died from circulatory disease, but higher levels of MMP-8 were found in patients who died from respiratory disease." (PMID 23031278, 2012). "GFRα2, RET, and MMP2 mRNA expression was analysed in lung macrophages from patients with COPD compared with patients with no underlying respiratory disease." (PMID 33020210, 2020).
infectious disease (2 papers, 2015 to 2022). A disorder directly resulting from the presence and activity of a microbial, viral, or parasitic agent in humans. "Matrix metalloproteinase (MMP)-2 and MMP-9, collectively known as the gelatinases, are closely associated with inflammatory and infectious diseases in a number of organs." (PMID 25523514, 2015). "MMPs, including MMP-2, MMP-3, and MMP-8, are involved in the pathogenesis of infectious diseases." (PMID 36142454, 2022).
vasculopathy (2 papers, 2024 to 2025). "Interleukin (IL)-8, IL-6, matrix metalloproteinase (MMP)-2, and MMP-9 levels were elevated in the cerebrospinal fluid of the patients with VZV vasculopathy." (PMID 39062454, 2024). "Elevated levels of proteases such as MMP-2 and MMP-9 disrupt basement membranes and tight junctions between endothelial cells, potentially contributing to inflammation and vessel wall damage, which are characteristics of VZV vasculopathy." (PMID 39062454, 2024).
CNS tumours (1 paper, 2012). "To assess the gene expression profile of hypoxia-induced genes in brain and CNS tumours, we queried the oncomine database for the following genes; HIF1A1, VEGFA, MMP2, NEDD9, SOX4, and SOX9." (PMID 22570651, 2012).
hematological malignancies (1 paper, 2013). "Considerable evidence has accumulated that MMP9 and MMP2 play an important role in the invasiveness and propagation of several hematological malignancies." (PMID 23289374, 2013).
muscular disorders (1 paper, 2007). "With respect to muscular disorders, particular attention has been paid to a subgroup of MMPs termed 'gelatinases,' comprising MMP-2 (also called gelatinase A, or 72-kDa type IV collagenase) and MMP-9 (also called gelatinase B, or 92-kDa type V collagenase)." (PMID 17598883, 2007).
musculoskeletal disorders (1 paper, 2013). "Serum TNF-α, IL-6, TGFB1, CTGF and MMP2 may serve as serum biomarkers of work-related musculoskeletal disorders, although further studies in humans are needed." (PMID 24015193, 2013).
MMP2 also shares sentences with these, for which no sentence is quoted: acute myocardial infarction (16 papers); chronic periodontitis (10); idiopathic pulmonary fibrosis (8); angina (6); chronic obstructive pulmonary disease (6); essential hypertension (6); gingivitis (5); hypertrophy (5); Glomerular sclerosis (4); metastasis (4); Pleural effusion (4); acute myocarditis (3); acute pancreatitis (3); acute promyelocytic leukemia (3); adrenocortical carcinoma (3); alcoholic cirrhosis (3); ameloblastic carcinoma (3); choriocarcinoma (3); diffuse astrocytoma (3); digestive system tumors (3); endometrial polyp (3); hyperthyroidism (3); intrahepatic cholangiocarcinoma (3); invasive ductal carcinoma (3); Kaposi's sarcoma (3); lung squamous cell carcinoma (3); membranous nephropathy (3); oligodendroglioma (3); penile squamous cell carcinoma (3); Peri-Implantitis (3).
A further 248 diseases each share a sentence with MMP2 in 3 papers or fewer.